MET (MET proto-oncogene, receptor tyrosine kinase)
Diseases named in the same sentence as MET in open-access papers (continued):
Sharing a sentence is not in itself a finding about the gene and the disease.
prostate carcinoma (continued). "These screens identified multiple therapeutic vulnerabilities of Snail+ prostate cancer cells, including several with known functions in prostate cancer and/or EMT, such as aurora kinases, MET, polo-like kinases, and CRM1/XPO1." (PMID 37228586, 2023). "Conversely, the core members (HGF, MET, and PIK3CA) were downregulated in the FOXP2 knockdown PC3 prostate cancer cells." (PMID 37668356, 2023). "We identified potential FOXP2-binding fragments located in MET and HGF in prostate cancer LNCaP cells." (PMID 37668356, 2023). "Previous studies have reported that the receptor tyrosine kinase MET and its ligand HGF are important for the growth and survival of several tumor types, including prostate cancer." (PMID 37668356, 2023). "These analyses identified multiple actionable targets, such as XPO1, PI3K/mTOR, aurora kinases, c-MET, polo-like kinases, and JAK/STAT as synthetic lethalities in Snail+ prostate cancer." (PMID 37228586, 2023). "In prostate cancer, co-expression of RON and MET promotes metastasis though ERK1/2 pathway activation." (PMID 35454943, 2022). "However, MeT did not significantly increase the number of γH2AX foci, a marker of DSBs, suggesting that DNA damage is not a major mechanism underlying its growth-suppressive activity in prostate cancer cells." (PMID 36923279, 2022). "The overall goal of this study was to elucidate the role of FGFR1 induction in acquired resistance to MET and VEGFR2 inhibition by cabozantinib in prostate cancer (PCa) and leverage this understanding to improve therapy outcomes." (PMID 31963871, 2020). "Here, we show that SEMA3C is a secreted soluble autocrine growth factor that drives growth and treatment resistance of prostate cancer via activation of multiple RTKs such as EGFR, MET, and ErbB2 in a cognate ligand‐independent manner." (PMID 29348142, 2018). "In summary, this study identifies SEMA3C as a key secreted, autocrine growth factor that drives PCa growth and castration‐ and treatment‐resistant prostate cancer progression through activation of EGFR, HER2/ErbB2, MET, and c‐SRC tyrosine kinase pathways." (PMID 29348142, 2018). "Since we have previously shown that N-cadherin is the most representative marker for epithelial-mesenchymal transition in clinical prostate cancer, these findings indicate that the HGF/MET pathway plays a minor role in early hormone-naive prostate cancer." (PMID 27105539, 2016). "Tyrosine-kinase inhibitor Cabozantinib, which targets both MET and VEGFR2, is currently under investigation for its effects on metastasized prostate cancer." (PMID 27105539, 2016). "Moreover, an inverse relationship between androgen level and c-MET expression has been observed in prostate cancer cell lines, suggesting that androgen deprivation, the current approach to metastatic PC may negatively contribute to disease response by increasing the expression of c-MET." (PMID 25277255, 2014). "The aim of this study was to clarify the prevalence and prognostic role of c-MET expression in prostate cancer by using a pre-existing tissue microarray (TMA) including more than 4,000 prostate cancers, the majority with clinical follow-up data." (PMID 23251249, 2013). "Further, c-MET activation led to a 3.25-fold enrichment of CD44+/CD24− cells, representing more accurately the stem-like cell profile for breast and potentially prostate cancer." (PMID 22110593, 2011). "In previous studies in human prostate cancer, it was suggested that GPX3 exhibits tumor suppressor activity by transcriptional regulation of the oncogene MET." (PMID 21106063, 2010). "FYN is downstream of the HGF/MET signaling loop, and HGF can effectively regulate FYN activity, which promotes prostate cancer biology by promoting cell growth and regulating targeted chemotaxis-translocation components in prostate cancer biology." (PMID 36740671, 2023).
prostate carcinoma (continued). "The Phase I study NCT02207504 focused on the maximum tolerated dose (MTD), associated toxicities, and pharmacokinetic profile of crizotinib, a c-MET/RON small molecule inhibitor alone and in combination with standard dosing of enzalutamide in castration-resistant prostate cancer patients." (PMID 35454943, 2022). "Congruently, targeting MET in CRPC clinical trials has shown no anticancer activity, suggesting that MET activity is not a primary driver of tumor progression in prostate cancer patients." (PMID 33471819, 2021). "While there has been little research focused on the modulating function of SIPA1 on the regulation of HGF/MET in TJs, previous work from the host laboratory indicated that in breast and prostate cancer cells, the presence of SIPA1 was required for the regulation of HGF/MET in TJs." (PMID 33917539, 2021). "Moreover, the positive correlation of RON expression with MET has been reported in prostate cancer, and patients with RON and MET co-expression had the lowest 10-years disease-free survival in node-negative breast cancer." (PMID 31867280, 2019). "At present, two anti-angiogenic drugs are being tested in the phase III setting for men with prostate cancer, carbozantinib (a dual VEGFR2/MET inhibitor) and tasquinimod (down-regulator of HIF-1α), which previously showed beneficial and encouraging results on phase II trials." (PMID 28143503, 2017). "None of the hormone-naive primary prostate cancer or lymph node metastases demonstrated MET protein or mRNA expression." (PMID 27105539, 2016). "C-terminal MET protein expression was neither found in hormone-naive primary prostate cancer nor lymph node metastasis." (PMID 27105539, 2016). "c-MET, a close homolog of RON, is suppressed by AR in prostate cancer cell lines." (PMID 26872377, 2016). "Albeit low to absent in hormone-naive prostate cancer, MET expression was found in HRPC specimens and bone metastases." (PMID 27105539, 2016). "Intriguingly, in GTL-16 cells selected with the MET inhibitor we have found a murine truncated Braf sequence that is homologous and share exactly the same predicted open reading frame of a rearranged BRAF found in human prostate cancer." (PMID 25473895, 2015). "Although c-MET appears to be involved in the progression of prostate cancer, this study does not confirm a role of c-MET as a prognostic marker in patients with prostate cancer." (PMID 23251249, 2013). "Previous RT-PCR and Northern blot analysis demonstrated that c-MET is expressed in androgen-independent prostate cancer cell lines DU145 and PC3, but not in androgen-dependent LNCaP." (PMID 22110593, 2011). "Considering the lack of alternative HGF/c-MET models for prostate cancer, we specifically aimed at validating our results in human prostate cancer specimens." (PMID 22110593, 2011). "Furthermore, the human c-MET receptor in prostate cancer xenografts has low sensitivity for murine HGF, so that external human HGF sources or transgenic mice are required for functional HGF/c-MET analysis." (PMID 22110593, 2011). "Indeed, most studies on the HGF/MET-mediated phosphorylation of STMN1 have not used prostate cancer cell lines, nor have they investigated in detail the regulation of both tSTMN1 and STMN1 phosphorylation during cell cycle progression." (PMID 40723207, 2025). "Overall, these results suggest that ETV1 and ERG, as well as MET activation, play an important role in prostate cancer cell migration and invasion, without affecting proliferation, and that MET receptor activation leads to an increase in these responses and MET repression to reversion." (PMID 39374163, 2025). "This knowledge provides a new basis for the development of MET‐targeted therapies, which could interfere with MET signalling pathways and, consequently, with ETS transcription factors, thereby reducing progression to the aggressive stages of prostate cancer." (PMID 39374163, 2025).
prostate carcinoma (continued). "Thus, our results demonstrate for the first time in prostate cancer models a functional interaction between ETS transcription factors (ETV1 and ERG) and MET signalling that confers more aggressive properties and highlight a molecular signature characteristic of this combined action." (PMID 39374163, 2025). "Thus, separately, ETV1, ERG and MET are well known to induce tumour properties in different cancers but their concomitant activity in prostate cancer is not yet described." (PMID 39374163, 2025). "In addition, FASN enhances the production of membrane RTKs, including EGFR, ERBB2, and hepatocyte growth factor receptor/c-MET, in breast, ovarian, and prostate cancers, as well as non-Hodgkin lymphoma." (PMID 38933330, 2024). "Indeed, by knocking down PHF19L, we observed significant induction of multiple genes known to promote changes in cytoskeleton and adhesion, extracellular matrix remodeling, invasion, and metastasis in prostate cancer (including SOX9, SOX4, MMP1, PLAU, EPCAM, CXCR4, LOX, and MET)." (PMID 32155117, 2020). "None of the 481 hormone-naive prostate cancer samples revealed MET expression." (PMID 27105539, 2016). "In addition, a noted increase in the amount of MET protein, another known target of miR-125b expression, would lead to an increase in RAS signaling thru the pMEK/pERK pathway, also shown to be increased in prostate cancer and supported by our proteomic data." (PMID 26544868, 2015). "The c-MET protein is often overexpressed in prostate cancer, but has no prognostic relevance." (PMID 23251249, 2013). "In contrast to JQ1, ivermectin also downregulated the expression of EMT genes, such as MET, MMP7, and SOX9, and did not induce EMT in prostate cancer." (PMID 36050295, 2022). "In conclusion, MET was almost exclusively expressed in HRPC and prostate cancer bone metastasis, but was not related to MET amplification or polysomy." (PMID 27105539, 2016). "The data show an abundant expression of c-MET and demonstrate that c-MET protein analysis does not serve as a prognostic marker for prostate cancer patients." (PMID 23251249, 2013).
colon carcinoma (129 papers, 2005 to 2025). "After obtaining the conclusion that c-MET caused an increase invasion of colon cancer cells, we conducted cell proliferation experiments of c-MET on HCT116 and SW480 cell lines." (PMID 35874635, 2022). "In a series of solid tumor specimens, including 43 colon cancer samples, MET exon 14 skipping mutations were identified in five cases (9.3%) with colon cancer." (PMID 34943612, 2021). "Other germ-line MET mutations occur in liver metastasis from colon cancer and hepatocellular carcinoma cause the gene to be over amplified." (PMID 29231907, 2017). "MET activating mutations in cancer have been described in renal papillary carcinomas, hepatocellular carcinomas, small-cell lung cancer and colon cancers." (PMID 28420162, 2017). "A recent study in vitro identified that concomitant downregulation of miR-1 and increase of metastasis-associated in colon cancer 1 (MACC1) can contribute to MET overexpression and to the metastatic behavior of colon cancer cells." (PMID 25196260, 2014). "A germline mutation in the MET gene, p.T992I, was identified in ~4.5% of colon cancers arising in first-degree relative pairs from two separate cohorts." (PMID 21970370, 2011). "MET mutations (or MET amplification /overexpression) which trigger ligand- independent activation of signaling, are relatively rare in human cancer and occur in approximately 6% of colon cancers." (PMID 27121052, 2016). "To evaluate the possibility that germline changes in the MET gene may lead to colon cancer susceptibility in a familial setting, we scanned and sequenced all coding exons of MET in our sibling pair cohort." (PMID 21970370, 2011). "Because amplification of the MET gene occurs in colon cancers, we hypothesized that the allele harboring p.T992I would be preferentially amplified in colon tumors." (PMID 21970370, 2011). "The MET mutations, R970C and T992I, were detected in 8 out of 239 C-07 colon cancers." (PMID 20233444, 2010). "Pathway analysis indicates that the over-expressed genes largely populate a dense network involved in cell proliferation and migration, including VEGF-A, PLAU and MET (HGF receptor), which have been implicated in control of cellular invasion and in colon cancer specifically." (PMID 17192196, 2006). "The Wnt target MET has been implicated in the development of colon cancer." (PMID 15785735, 2005). "We have also found that GALNT2 was able to mildly regulate the phosphorylation of EGFR and MET in colon cancer cells." (PMID 36409270, 2023). "Further, matching the IGF2BP1 interactome data with transcriptomic data, we have found 17 common genes, including MGAT5 and MET, which showed a higher degree of expression in colon tumors analyzed from the TCGA database." (PMID 37829185, 2023). "Inhibiting or knocking MET down made colon cancer cells sensitive on cetuximab-mediated growth inhibition, implicating that targeting MET was a rational strategy for reversing cetuximab resistance in colon cancer." (PMID 34983358, 2022). "The inhibition of MET alone has been demonstrated to have limited efficacy in colon cancer; although the Src inhibitor, dasatinib, reduced MET autophosphorylation and decreased MET phosphorylation by stimulating factors, the inhibition is not complete." (PMID 36430388, 2022). "Meanwhile, the expression of c-MET in colon cancer cells varied with the change of MACC1 and showed positivity for colon cancer, and c-MET promoted the development and progression of colon cancer." (PMID 35874635, 2022). "The aim of this study was to investigate the role of the HGF/c-MET axis in the proliferation and metastasis in colon cancer." (PMID 35874635, 2022). "Previously, we found that Src and MET were upstream kinases of TOPK, and the phosphorylation of TOPK by Src and MET promoted the tumorigenesis of colon cancer and resistance of NSCLC to gefitinib, respectively." (PMID 36167821, 2022).
colon carcinoma (continued). "According to the results of in vitro experiments, the recession of MACC1 and c-MET in colon cancer cells can indeed regulate the proliferation and migration of cancer cells." (PMID 35874635, 2022). "Wound healing results showed that c-MET overexpression accelerated the migration rate of colon cancer cells (P < 0.01), while si-c-MET slowed the migration rate (P < 0.01)." (PMID 35874635, 2022). "This experiment showed that there was also an upstream-downstream relationship between MACC1 and c-MET in colon cancer cells and tissues, both of which formed the MACC1/HGF/c-MET axis." (PMID 35874635, 2022). "Specifically, inhibition of the MACC1/HGF/c-MET axis contributes to the treatment and prognosis of colon cancer and also helps to suppress the proliferation and invasion of colon cancer cells." (PMID 35874635, 2022). "MACC1, a critical modulator of the HGF/MET signaling pathway, was revealed to predict colon cancer metastasis." (PMID 34939526, 2022). "It is not difficult to find a close relationship between MACC1 and c-MET as well as HGF in colon cancer by extracting data from StarBase Pan-cancer." (PMID 35874635, 2022). "MACC1, the MET transcriptional regulator, also promotes metastasis and recurrence of colon carcinoma by activating the HGF/c-Met signaling pathway." (PMID 35069196, 2021). "Clinical trials for MET inhibitors have demonstrated limited success for their use in colon cancer (CC)." (PMID 34428346, 2021). "Upregulation of the IGF1R pathway constitutes a common paradigm shared with other receptor tyrosine kinases such as EGFR, HER2, and MET in different cancer types, including colon cancer." (PMID 34065119, 2021). "Overexpression of RAB31 in CAFs promoted colon cancer cell migration in an HGF/MET-dependent manner, suggesting a role for CAF-expressed RAB31 in the migration of colon cancer cells through regulating paracrine secretion of HGF." (PMID 33072555, 2020). "In our previous study, we demonstrated a role of the hepatocyte growth factor (HGF)/MET pathway in the regulation of colon cancer cell proliferation and cetuximab resistance." (PMID 28573382, 2017). "MET activation also promotes the cancer stem cell phenotype in several other types of cancer, including gliomas, colon cancer, head and neck cancer, prostate cancer and pancreatic cancer." (PMID 28420162, 2017). "HGF/MET signaling has been linked to resistance to EGFRI therapy in many types of cancer, like NSCLC (gefitinib) and colon cancer (cetuximab)." (PMID 28456787, 2017). "In the present study, we focused on the impact of the HGF/MET pathway on Chk1 activity, taking into account previous findings of a role of the MET pathway in regulation of cell proliferation and cetuximab resistance in colon cancer cells." (PMID 28573382, 2017). "Co-inhibition of EGFR and MET promotes eradication of colon cancer stem cells, resulting in durable tumor regression." (PMID 28420162, 2017). "Together these data demonstrate that SRI31215 inhibits autocrine or paracrine HGF/MET signaling and thus averts the resistance of colon cancer cells to EGFRi." (PMID 27121052, 2016). "In this study, we identified that cetuximab-induced MET activation contributed to cetuximab resistance in Caco-2 colon cancer cells." (PMID 24714091, 2014). "A recent study reported the emergence of MET amplification during anti-EGFR therapy eventually limited the efficacy of further treatment in colon cancer." (PMID 24714091, 2014). "MACC1 functions as a key activator of the HGF/c-MET signaling pathway, promoting colon cancer cell proliferation, invasion and metastasis in culture, and the growth and metastasis of tumors in xenograft models." (PMID 25009663, 2014). "A recent study has demonstrated that HGF-dependent MET activation contributes to cetuximab resistance in colon cancer." (PMID 24714091, 2014). "In summary, we showed that MET activation induced by cetuximab is a novel resistance mechanism to cetuximab in colon cancer cells." (PMID 24714091, 2014).